MALAT1 (metastasis associated lung adenocarcinoma transcript 1)
Diseases named in the same sentence as MALAT1 in open-access papers (continued):
Sharing a sentence is not in itself a finding about the gene and the disease.
cancer (continued). "Studies on the diagnostic performance of MALAT-1 in cancers were retrieved by searching the online databases." (PMID 29254244, 2017). "lncRNAs metastasis associated lung adenocarcinoma transcript 1 (MALAT1) have been found to be up-regulated in some human cancers." (PMID 28396617, 2017). "One of the most well-characterized and described lncRNAs in cancer is the “metastasis-associated lung adenocarcinoma transcript 1” (MALAT1), a rather atypical lncRNA with a high expression and species conservation." (PMID 28270163, 2017). "Up-regulation of MALAT1 in NSCLC is associated with cancer metastasis and is a biological marker used to predict disease outcomes in patients with early-stage NSCLC." (PMID 27802187, 2017). "At last, 14 studies assessed the diagnostic utility of up-regulated MALAT-1 in cancer were included in the statistical analysis." (PMID 29254244, 2017). "Metastasis associated lung adenocarcinoma transcript 1 (MALAT1) is a well-known cancer-related lncRNA over 8,000 nt in length." (PMID 29632545, 2017). "NEAT2/MALAT1 is a highly conserved lncRNA associated with tumorigenesis and plays a prognostic role in various cancers." (PMID 28293170, 2017). "For instance, the lncRNA metastasis-associated lung adenocarcinoma transcript 1 (MALAT1) was found to be overexpressed in numerous kinds of cancer cells, to regulate the cell proliferation and inhibit the cell cycle." (PMID 28073380, 2017). "For example, MALAT1 (metastasis-associated lung adenocarcinoma transcript 1), a metastasis-related lncRNA universally expressed in a series of human cancers, was shown to promote migration and invasion of cancer cells." (PMID 28423732, 2017). "Since it was discovered nearly a decade ago, an accumulated large amount of data have linked MALAT1 to many cancer types." (PMID 27486823, 2016). "Further studies are also necessary to elucidate roles of these different MALAT1 transcript variants in breast tumourigenesis and their genetic (or epigenetic) dysregulation molecular mechanisms in this cancer." (PMID 27172249, 2016). "The long non-coding RNA (lncRNA) metastasis-associated lung adenocarcinoma transcript 1 (MALAT1) has been recently shown to be dysregulated in several cancers." (PMID 26918449, 2016). "Long non-coding RNA (lncRNA) metastasis-associated lung adenocarcinoma transcript 1 (Malat1) functions as an oncogene in many types of human cancer." (PMID 27191262, 2016). "Recently, intensive research has focused on MALAT1, and it has been linked to many types of human cancers." (PMID 27092491, 2016). "A very notable example among lncRNAs found upregulated in pathological samples, is MALAT1 that has been widely reported to be upregulated in a large variety of solid tumors in association with progression and cancer metastasis." (PMID 26895470, 2016). "In most cases, MALAT-1 is upregulated in cancer and is associated with metastasis, cell proliferation, apoptosis, and migration, as well as with clinically unfavorable prognostic parameters." (PMID 27608009, 2016). "A number of studies have revealed that overexpression of MALAT1 was significantly associated with high-risk grade, metastasis and patients’ survival in many types of cancers." (PMID 27777857, 2016). "RT-PCR-based splicing assays revealed that MALAT1-overexpressed cells showed changes in the SRSF-mediated alternative splicing of pre-mRNAs of several cancer–associated genes, including TEAD, BIN and BIM." (PMID 27250026, 2016). "MALAT1 overexpression has also been linked to cancer metastasis and tumor recurrence in patients following liver transplantation." (PMID 26634812, 2016). "High expression of MALAT-1 was associated with high-risk grade, metastasis, and poor prognosis of cancer patients." (PMID 26989678, 2016). "From our literature review, we found that one of ten HublncRs, MALAT1, was a well-known prognostic marker linked to several cancers." (PMID 26863568, 2016).
cancer (continued). "The up-regulation of the MALAT1 expression was associated with the clinical parameters and poor prognostic outcome of cancer patients, this finding is consistent with our results." (PMID 27527868, 2016). "The results revealed that elevated MALAT1 expression was significantly associated with poor overall survival (OS) in 11 types of cancers (HR = 1.91, 95 % CI 1.49–2.34)." (PMID 27777857, 2016). "Human cancer metastasis is associated with lung adenocarcinoma transcript 1 (MALAT-1), a long non-coding RNA that consists of more than 8,000 nt and is located on chromosome 11q13." (PMID 26637808, 2016). "Overexpression of MALAT-1 was associated with high-risk grade, metastasis, and poor prognosis of cancer patients." (PMID 26989678, 2016). "MALAT1 is a nuclear long non-coding RNA, whose expression has associated with a migratory phenotype and tumor stem regulation in several cancer types." (PMID 27015363, 2016). "Many studies have shown that MALAT1 is over-expressed in many solid tumors and associated with the proliferation and metastasis of several other cancers." (PMID 27564100, 2016). "Metastasis associated in lung adenocarcinoma transcript-1 (MALAT-1) is overexpressed during cancer progression and promotes cell migration and invasion in many solid tumors." (PMID 27227769, 2016). "MALAT1 (metastasis associated lung adenocarcinoma transcript 1), also called NEAT2 (nuclear enriched abundant transcript 2), is a type of long nuclear-retained transcript that was shown to be associated with cancer cell metastases." (PMID 27196897, 2016). "MALAT-1 is also associated with cell migration in cancer cells, we next tested the effects of asRNA on cell migration in Hela cell and MDA-MB-231 cell." (PMID 27231846, 2016). "Meanwhile, another group reported that MALAT-1 can also serve as a urinary biomarker for high-risk cancer prediction." (PMID 26690121, 2015). "Co-culturing PC3 cells with WT osteoblasts up-regulated cancer-associated long noncoding RNA (lncRNA) MALAT1 in PC3 cells." (PMID 27600237, 2015). "MALAT1 is also implicated in metastasis; chromosomal translocation is the main mechanism behind its marked upregulation in cancer." (PMID 26064090, 2015). "High expression levels of the long non coding RNA MALAT1 are associated with aggressive proliferation, metastasis and recurrence in a variety of cancers." (PMID 25849371, 2015). "MALAT1 (Metastasis Associated Lung Adenocarcinoma Transcript1) is another prominent lncRNA implicated in a variety of cancers." (PMID 26082843, 2015). "Another paradigmal case of lncRNA based cancer biomarkers is MALAT1 (Metastasis-associated Lung Adenocarcinoma Transcript 1)." (PMID 25954300, 2015). "The mechanism underlying the relationship between elevated MALAT1 expression and poor prognosis in patients with various types of cancer is uncertain." (PMID 26420912, 2015). "Other in vitro studies, have implicated MALAT1 in the regulation of the invasive potential of cancer cells, in cervical and lung cancers." (PMID 25275300, 2014). "MALAT1 resides on chromosome 11q13.1 which has been found to harbor chromosomal translocation breakpoints linked to cancer." (PMID 25275300, 2014). "The lncRNA metastasis-associated lung adenocarcinoma transcript 1 (MALAT1) is overexpressed in several human cancers, including PCa." (PMID 25243154, 2014). "MALAT1 is up-regulated in many solid tumours, and is associated with cancer metastasis and recurrence." (PMID 24702795, 2014). "MALAT1 expression is typically upregulated in cancer and has been associated with several neoplastic phenotypic features including proliferation, cell death, migration, invasion, and metastasis." (PMID 25400658, 2014). "On the contrary, MALAT1 was documented by several studies to associate with metastasis in other cancer types." (PMID 23862139, 2013). "The lncRNA MALAT1 is upregulated in several solid tumors and its differential expression is linked with cancer metastasis and recurrence." (PMID 23555285, 2013).
cancer (continued). "A number of studies have implicated MALAT1 in the regulation of cell mobility, due to its high levels of expression in cancers." (PMID 23443164, 2013). "The long noncoding MALAT1 RNA is upregulated in cancer tissues and its elevated expression is associated with hyper-proliferation, but the underlying mechanism is poorly understood." (PMID 23555285, 2013). "Our data indicates that the cancer-associated MALAT1 RNA regulates cellular proliferation by modulating the expression and/or pre-mRNA processing of cell cycle–regulated transcription factors." (PMID 23555285, 2013). "Metastasis associated lung adenocarcinoma transcript 1 (Malat1) is a highly conserved 8.7 kb non-coding transcript that is abundantly expressed in cancer cells and a strong predictor of metastasis." (PMID 24084719, 2013). "MALAT1, an abundant nuclear-retained lncRNA, is overexpressed in several cancers, and its elevated expression has been associated with hyper-proliferation and metastasis." (PMID 23555285, 2013). "The MALAT1 locus at 11q13.1 has been identified to harbor chromosomal translocation break points associated with cancer." (PMID 23443164, 2013). "For example, two ncRNAs, PCGEM and DD3, are significantly over expressed in prostate cancer, HULC expression is significantly associated with hepatocellular carcinoma and MALAT1 is known to be over expressed in several human carcinomas." (PMID 19379481, 2009). "MALAT1 and H19 secretion have been linked to increased growth and transformation of cancer cells." (PMID 41181715, 2025). "Among them, lncRNA metastasis-associated lung adenocarcinoma transcript (MALAT1) has been implicated in the pathogenesis of various cancers, including esophageal, cervical, and laryngeal cancers, where it influences tumor cell proliferation, apoptosis, invasion, and metastasis." (PMID 39319867, 2025). "Blocking cancer‐causing RNAs such as MALAT1 or H19 may interfere with the ways that tumors stay alive through autophagy and make cancer cells more sensitive to traditional chemotherapies." (PMID 40671967, 2025). "MALAT-1, the oncogenic lincRNA, seems to be a crucial biological modulator that is closely associated with the onset, spread, and responsiveness to the treatment of cancer as well as has been implicated in the interruption of cellular homeostasis." (PMID 39912974, 2025). "Studies have found that MALAT1 is associated with cancer invasion and metastasis." (PMID 40313963, 2025). "On the genetic level, MALAT-1 has the strongest correlation with genes related to immunological regulation, cellular development, motility, proliferation, and signaling that are implicated in cancer." (PMID 39912974, 2025). "Additionally, MALAT1 has emerged as a promising diagnostic and therapeutic target across multiple cancer types." (PMID 39319867, 2025). "MALAT1 is highly expressed in various cancer tissues and associated with poor prognosis." (PMID 40597438, 2025). "Previous reports observed a link between Malat1 and β-catenin signaling pathway in cancers 34,35, but the underlying molecular mechanisms in terms of how Malat1 interacts with β-catenin and regulates its nuclear retention and transcriptional activity are unclear." (PMID 38234849, 2024). "Indeed, MALAT1, like other lncRNAs, has been shown to be involved in AS by interacting with SFs to favor splicing variants that promote cancer development due to anti-apoptotic (BIM, BIN1) and pro-proliferative properties (TEAD1)." (PMID 38674413, 2024). "However, other studies have reported decreased MALAT1 expression in some types of cancers, as well as the association of low MALAT1 levels with advanced clinical stages and metastases." (PMID 38255996, 2024). "Similarly, the association of lncRNA MALAT1 with tumor growth and metastasis in colorectal cancer positions it as both a diagnostic marker and a therapeutic target, reflecting its dual role in cancer management." (PMID 39716252, 2024).
cancer (continued). "We will also discuss the diagnostic and therapeutic applications of MALAT-1 in cancer therapy." (PMID 38511067, 2024). "LncRNA MALAT1 (Metastasis Associated Lung Adenocarcinoma Transcript 1) has been reported previously for its function in both cancer development and progression, playing critical roles in central carcinogenic mechanisms (i.e., proliferation, apoptosis, tumorigenicity, etc.)." (PMID 38785786, 2024). "In further support of the MUC1-C/XIST pathway, we found that MUC1-C and XIST regulate common genesets associated with activation of (i) miRNAs, such as miR-21, (ii) lncRNAs NEAT1 and MALAT1, and protein encoding genes that are linked to inflammation and dysregulated in cancer." (PMID 38740827, 2024). "A high level of MALAT1 expression is observed in cancers with high susceptibility to metastasize." (PMID 39725668, 2024). "The correlation between specific polymorphisms and cancer risk might be explained by the alternations in MALAT1 expression." (PMID 38674413, 2024). "Additionally, these small molecules serve as valuable molecular probes in research settings, allowing for precise study of the mechanisms underlying MALAT1-driven cancers." (PMID 39015773, 2024). "MALAT-1, one of these lncRNAs, has been linked to many cancers, such as breast, lung, and HCC." (PMID 38511067, 2024). "Accordingly, the MALAT1 polymorphisms have been examined in regard to cancer risk contribution." (PMID 38674413, 2024). "MALAT1 is overexpressed and displays increased mutations in many cancer types." (PMID 39199690, 2024). "MALAT1 can be a therapeutic target, potential diagnostic, and prognostic biomarker for cancers." (PMID 38328782, 2024). "MALAT1 (Metastasis-Associated Lung Adenocarcinoma Transcript 1): Identified in exosomes from various cancer cells, MALAT1 is associated with modulating T cell function and inducing the release of pro-inflammatory cytokines, thus contributing to metabolic reprogramming and immune cell polarization." (PMID 37760852, 2023). "MALAT1 associated cancer signaling pathways include MAPK/ERK, β-catenin/Wnt, PI3K/AKT." (PMID 37283796, 2023). "In this review, we introduced the main mechanisms of chemotherapy resistance associated with MALAT1, which may provide new approaches for cancer treatment." (PMID 36829256, 2023). "Furthermore, the lncRNA metastasis-associated lung adenocarcinoma transcript 1 (MALAT1), upregulated in various types of cancers, promotes LC proliferation and metastasis by acting as ceRNA for anti-metastatic miR-200a, inducing ZEB1 TF expression." (PMID 37464436, 2023). "Interestingly, MALAT1 was one of many lncRNAs that we found to encode an antigenic peptide, thus extending the significance of MALAT1 in cancer by connecting its lncRNA expression with a derived peptide and antigen presentation." (PMID 36841868, 2023). "This upper limit of MALAT1 function may be due to a protective mechanism from too much of a lncRNA that is often associated with cancer." (PMID 37620957, 2023). "Additionally, long non-coding RNAs (lncRNAs), exemplified by metastasis-associated lung adenocarcinoma transcript 1 (MALAT1), exert critical roles in cancer biology." (PMID 37812599, 2023). "Furthermore, the metastasis-associated lung adenocarcinoma transcript 1 (MALAT1) has been reported to be associated with metastatic potential, and it was found to be upregulated in many cancers." (PMID 35327559, 2022). "Thus, we pooled current published studies and conducted a meta-analysis to explore the potential relationships between MALAT1 rs3200401 C > T and the risk of cancer." (PMID 35208500, 2022). "In addition, MALAT1 overexpression induced proliferation and metastasis of cancer cells associated with vascular and capsular invasion in HCC." (PMID 36685103, 2022).
cancer (continued). "The metastasis-associated lung adenocarcinoma transcript 1 (MALAT1) is one of these gene expression–controlling lncRNAs, and its aberrant expression has been implicated in the development and progression of many types of human cancers." (PMID 36563164, 2022). "Finally, another main field of research focuses on the role of a special category of lncRNAs, defined as intergenic, such as MALAT1, predominantly found in nuclear speckles, and which are associated with poor prognosis cancers." (PMID 35873564, 2022). "In fact, a strong upregulation of MALAT1 has been reported for a wide range of human cancers, while its tissue levels are also associated with the clinical characteristics of patients, including resistance to therapy, indicating it as an ideal clinical biomarker." (PMID 35804851, 2022). "Recently, studies have shown that the 8-kb lncRNA MALAT1 could be linked to other cancers, including breast cancer, prostate cancer, pancreatic cancer, glioma, and leukemia." (PMID 36685103, 2022). "Furthermore, studies found MALAT1 to be a potential diagnostic or prognostic biomarker in PCa and a potential therapeutic target in various cancer entities." (PMID 35159020, 2022). "MALAT1 overexpression has been linked to enhanced cell proliferation, invasion, metastasis, apoptosis evasion, a failure in the DNA repair process, and tumor-promoting inflammation; therefore, it can be used in cancer diagnosis and prognosis." (PMID 35159299, 2022). "Moreover, MALAT1 caused the silencing of genes intertwined with cancer progression and metastasis by recruiting chromatin-modifying complexes to target gene loci (e.g., E-cadherin and PCDH10)." (PMID 35656022, 2022). "Furthermore, plant miRNAs have also been reported to reduce cancer-cell proliferation by targeting MALAT1 (Metastasis-associated lung adenocarcinoma transcript 1) and NEAT1 (Nuclear-enriched abundant transcript 1)." (PMID 35456943, 2022). "Moreover, the association between MALAT-1 expression and cancer-specific survival was also investigated using the TCGA database." (PMID 35016717, 2022). "Interestingly, one of the highly expressed cancer-associated long non-coding RNA (lncRNA), MALAT1, was also significantly downregulated by HiA." (PMID 34445083, 2021). "Moreover, single nucleotide polymorphism in MALAT1, e.g., rs619586 A > G polymorphism, has also been witnessed to be linked with elevated cancer risks." (PMID 34885213, 2021). "MALAT1 as a highly m6A modified lncRNA associated with cancer development and metastasis, but the functional relevance of m6A methyltransferase and MALAT1 in BC is still unknown." (PMID 34419065, 2021). "The integration of the differentially expressed ncRNAs, with an exhaustive computational analysis of their experimentally supported targets, led us to dissect complex networks integrated by the cancer-related lncRNAs Malat1, Neat1, H19, Meg3, and their associated miRNA-target pairs." (PMID 34222014, 2021). "MALAT1 has been seen to be associated with different diseases, including cancer." (PMID 34885213, 2021). "Since that overexpressed MALAT1 has been reported to be linked with a wide variety of lymphoid or solid tumors with high tumor progression and metastasis propensity and 1.5–10 fold relative upregulation based on type and stage of cancer." (PMID 34885213, 2021). "According to this model, when there is a lack of methylation at A5044 in HeLa cells, a short hairpin is favored over a pseudoknot, thereby possibly increasing the accessibility of cancer-associated miR-101-3p, miR-217-5p, and miR-383-5p to their binding sites in MALAT1." (PMID 33450947, 2021). "MALAT1/NEAT2 is abundantly expressed and widely associated with a variety of cancers." (PMID 33799493, 2021). "Furthermore, several lncRNAs with critical roles in cancer development have been characterized, such as the Metastasis Associated Lung Adenocarcinoma Transcript 1 (MALAT1), promoting tumor growth and invasion." (PMID 34298698, 2021).